BDNF (brain derived neurotrophic factor)
Diseases named in the same sentence as BDNF in open-access papers (continued):
Sharing a sentence is not in itself a finding about the gene and the disease.
depression (continued). "Indeed, in depression, both neurotrophic factor BDNF and its high-affinity receptor TrkB have been shown to be decreased, at both the RNA and protein level." (PMID 27378793, 2016). "All of these studies indicated that BDNF plays critical roles in the pathogenesis of depression." (PMID 27642354, 2016). "Emotional disorders such as depression, generalized anxiety disorder and PTSD in humans have been shown to be associated with altered peripheral BDNF levels, and these peripheral levels are in turn postulated to reflect central BDNF signaling which is assumed to influence brain function." (PMID 26586578, 2016). "Taken all together, it is likely that increased BDNF–TrkB signaling in the NAc, due to a deletion of the α7 nAChR gene, may generate the depression-like phenotype seen in α7 nAChR KO mice." (PMID 27821848, 2016). "Thus, countless studies have reported decreased BDNF levels in serum in mood disorders, including depression, although by contrast physical exercise has been found to increase them." (PMID 27006395, 2016). "Patients suffering from depression exhibit specific BDNF levels reduction in hippocampus and serum." (PMID 26869919, 2016). "Some studies have confirmed that the BDNF signaling pathway is involved in CUMS induced depression." (PMID 27642354, 2016). "Interestingly, expression of BDNF was negatively correlated with miR-16 indicating the regulatory role of miR-16 in the development of depression." (PMID 27240359, 2016). "We examined the effect of EET on depression-like behavior and BDNF levels in WT and KIV mice during ED, young adult, and old adult stages and tested whether these effects persisted after 1 month without EET." (PMID 27648918, 2016). "The results of the present study suggest the potential of HMF as a novel anti-depressant drug based on the “BDNF hypothesis of depression”." (PMID 27120588, 2016). "Increased levels of proinflammatory cytokines, such as TNF-α and IL-6, have been associated with cases of depression and as per a recent study, inhibition of TNF-α prevents cognitive decline and maintains hippocampal brain-derived neurotrophic factor (BDNF) levels." (PMID 26835453, 2016). "Estimated serum BDNF means (s.d.)at admission and upon discharge were 48.1(24.5) and 51.3(22.6) in major depression; 45.4 (17.7) and 48.4 (20.0) in bipolar depression; 42.5 (20.7) and 53.1 (25.1) in manic episode; and 46.5 (21.8) and 49.1 (19.0) in schizophrenia." (PMID 27959329, 2016). "Especially with regard to depression, the decrement in neurotrophic factors (mainly BDNF) is a well-known pathogenesis hypothesis of depression." (PMID 26935651, 2016). "The serotonergic system, classically involved in the depression/anxiety mechanisms, is now proposed to regulate Aβ precursor protein (APP) activity and metabolism, while Brain Derived Neurotrophic Factor (BDNF) has a relevance not only in MD, but also in depression-associated cognitive decline." (PMID 26869919, 2016). "Furthermore, trophic stimuli such as brain-derived neurotrophic factor (BDNF) increase brain mitochondrial efficiency; however, this effect is blocked by inflammatory cytokines, which can contribute to depression." (PMID 26934888, 2016). "BDNF is involved in neuronal growth and differentiation that is crucial for the pattern of the developing peripheral nervous system, and is dysregulated in Alzheimer's disease, Parkinson's diseases, schizophrenia and depression." (PMID 27483351, 2016). "In conclusion, this study shows that adjunction of brexpiprazole to fluoxetine can produce a rapid antidepressant effect in the social defeat stress model of depression and that BDNF-TrkB signaling plays a role in the rapid antidepressant action of such combination therapy." (PMID 27991542, 2016).
depression (continued). "Further, there are several lines of evidence that suggest that downregulation of BDNF–TrKB–CREB signaling pathway may serve as a common link between the development of alcohol-induced depression-like symptoms and reduced hippocampal neurogenesis." (PMID 27766083, 2016). "The causal relationship between BDNF and depression is still controversial and a focus on BDNF alone does not take the full complexity of depression into account." (PMID 27494716, 2016). "Furthermore, genetic and functional evidence suggests that there is a dysregulated interaction between BDNF signaling and serotonergic neurotransmission in depression pathology." (PMID 28119573, 2016). "A recent meta-analysis on the gene-by environment interaction effects between BDNF Val66Met and stress on depression, lists two possible reasons for null findings: firstly the use of child and adolescent cohorts and secondly the use of objective measurements such as interviews." (PMID 27267363, 2016). "Additionally, Alder and Thakker-Varia suggest that BDNF plays a role in neuronal plasticity, particularly emotional processing networks that are compromised in depression." (PMID 27621711, 2016). "BDNF is the most abundant neurotrophic factor in the brain and plays an important role not only in neural development, survival, and function, but also in neurogenesis and neuroplasticity, both of which are important targets for depressive disorder treatments." (PMID 27120588, 2016). "Another gene that may modulate the impact of stress on depression vulnerability is the brain-derived neurotrophic factor (BDNF)." (PMID 26005424, 2015). "On balance, available evidence suggest that low BDNF is predictive of incident and prevalent depression and that normalization of BDNF levels may be indicative of treatment of depression." (PMID 25886523, 2015). "To date, many studies have revealed that several neurotrophic factors, including but not limited to BDNF, and related signaling transduction pathways might be involved in the pathogenesis of depression." (PMID 26633366, 2015). "Taken together, we propose a research framework that community dwelling women may respond to an exercise program with rhythmic music that stimulates increased BDNF and immune parameters resulting in a reduction in depression symptoms." (PMID 26075212, 2015). "Among patients with depression, a correlation was found between cognitive functions and BDNF." (PMID 26405456, 2015). "They found that exercise could increase the neurotransmission of a neural substance, BDNF, which has been proven to reduce the effects of depression and anxiety as well as bringing comfort." (PMID 26075212, 2015). "Polymorphisms of the brain-derived neurotrophic factor (BDNF) have been investigated as candidate genes for post-stroke depression (PSD), and its receptor, neurotrophic tyrosine kinase receptor B (TrkB), has been associated with depression." (PMID 26641254, 2015). "It has been shown that direct injection of BDNF into the dentate gyrus or CA3 subfield of the hippocampus exerts an antidepressant effect and the antidepressant-like effect mediated by paroxetine is enhanced in rodent models of depression; enhanced BDNF signaling enhances mood." (PMID 26569216, 2015). "Interestingly, patients with depression who received an 8–12-week course of treatment with antidepressant medications exhibited a significant increase in the serum BDNF concentration." (PMID 26075212, 2015). "Moreover, postmortem studies in depressed patients showed reduced expression of BDNF mRNA and protein levels in the hippocampus and prefrontal cortex as well as in the serum and plasma of patients with depression." (PMID 25739024, 2015). "Our findings suggest that using early increases in serum BDNF as a treatment biomarker in future investigations might be useful for identifying individuals resilient to major depressive disorder after a traumatic event." (PMID 26151924, 2015).
depression (continued). "We confirmed our previous findings in the present study, showing that peripheral BDNF levels diminished similarly in both manic and depressive episodes of BD and were normal in euthymia, and extended our findings by also showing that BDNF levels are decreased in tandem with severity of symptoms." (PMID 26621529, 2015). "The regulation of the brain-derived neurotrophic factor (BDNF) is important for depression pathophysiology and epigenetic regulation of the BDNF gene may be involved." (PMID 26285129, 2015). "Our findings thus highlight the potential for BDNF methylation in buccal tissue to be a biomarker of depression, but further large prospective longitudinal studies are needed to confirm our findings and reveal the temporal relationship of the observed associations." (PMID 26285129, 2015). "This study was further broadened to investigate whether MAE could improve depression symptoms and blood BDNF levels in community dwelling women after a 12-week MAE program." (PMID 26075212, 2015). "In addition, chronic treatment with quetiapine attenuates the decrease in cortical and hippocampal BDNF expression that occurs in different animal models of depression." (PMID 25667608, 2015). "Thus, the decreasing BDNF in patients with depression seems to reflect such types of neurodegeneration." (PMID 26405456, 2015). "We then investigated whether subchronic arsenic exposure could induce or enhance anxiety- or depression-like behaviors through downregulation of BDNF-TrkB signaling pathway." (PMID 26114099, 2015). "After adjusting for confounding, women whose serum BDNF levels were in the lowest three quartiles (<17.32 ng/ml) had 1.61-fold increased odds (OR = 1.61, 95% CI: 1.13, 2.30) of antepartum depression as compared with women whose BDNF levels were in the highest quartile (>25.31 ng/ml)." (PMID 25886523, 2015). "Thus, enhancing monoaminergic tone, and consequently central BDNF expression, modulates pain-depression behaviors." (PMID 26342110, 2015). "The previous studies in other psychiatric disorders such as major depression and bipolar illness have strongly suggested BDNF serum levels may be used as a biomarker for onset or progression of symptoms or improvement after treatment." (PMID 26866045, 2015). "In addition, we will collect blood samples in order to investigate the (predictive) role of several physiological processes (e.g. oxytocin, brain-derived neurotrophic factor, DNA methylation and RNA markers) during the course of psychotherapy for depression." (PMID 26122891, 2015). "A separate genetic risk factor, the BDNF Val66Met polymorphism, has been reported to stratify AD patients with and without co-morbid depression." (PMID 25806005, 2015). "After adjusting for confounders, women whose serum BDNF levels were in the lowest three quartiles (≤25.31 ng/ml) had 1.61-fold increased odds (OR = 1.61; 95% CI: 1.13, 2.30) of antepartum depression as compared with women whose BDNF levels were in the highest quartile (>25.31 ng/ml)." (PMID 25886523, 2015). "Some of the changes in leptin may be mediated to some degree by decrease in BDNF which are observed in depression." (PMID 26231223, 2015). "BDNF was unchanged, although we expected a decrease in analogy to major depression." (PMID 26500502, 2015). "Furthermore, in the hippocampus, decreased BDNF has been found in chronic inflammatory pain states, and this decrease has been shown to be responsible for depression-like behaviors." (PMID 25810926, 2015). "Many of the metabolic aspects of depression could be mediated through the actions of cortisol and BDNF." (PMID 26231223, 2015). "The association between improvement of depression in previous studies and minimization of developing depression in the present study and increased serum BDNF might reflect intervention time effects." (PMID 26151924, 2015).
depression (continued). "For example it has been shown that targeted or inducible deletion of the BDNF gene produces behavioral dysfunction related to anxiety and depression, suggesting that such changes may contribute to the pathologic condition." (PMID 25873859, 2015). "The objectives of the present study were to verify whether older women with anxiety disorder/depression differ from control subjects according to DNA methylation and genotypes at SNVs in BDNF, OXTR, SLC6A4, and APOE." (PMID 26175754, 2015). "Most importantly, BDNF levels are ubiquitously decreased across diverse psychiatric pathologies, and decreased in both poles of BD – mania and depression – when one would possibly expect opposite behaviours if its levels were causally related to the development of a mood episode." (PMID 26621529, 2015). "Recently, using meta-analytic techniques, we established that peripheral BDNF levels are decreased in schizophrenia and in major depressive disorder, and that the extent of the decrease is indistinguishable among acute mood states and schizophrenia along the schizoaffective continuum." (PMID 26621529, 2015). "BDNF has frequently been found to be reduced in patients with depression with the implication being that reduced levels of BDNF may be a suitable biomarker for depression." (PMID 26231223, 2015). "The BDNF signaling in neurons is decreased in depressed patients and animal models of depression." (PMID 26317356, 2015). "Indeed, there is a consensus that both circulating and brain BDNF levels are decreased in depression." (PMID 26469350, 2015). "However, further studies are necessary to define a functional role of BDNF in preventing the development of depression." (PMID 26379544, 2015). "In addition, orexin promotes the expression of BDNF, which regulates neuronal plasticity and is reduced in the blood serum of depression patients." (PMID 25884812, 2015). "In patients with depression the levels of BDNF are very low." (PMID 26180581, 2015). "Compared with BDNF levels in the highest quartile (>25.31 ng/ml), women with lower levels (≤25.31 ng/ml) had a 1.61-fold higher odds of antepartum depression (OR = 1.61; 95% CI: 1.13-2.30) after adjustments for confounding factors including maternal age, parity and early pregnancy body mass index." (PMID 25886523, 2015). "Although the difference between those in acute manic and depressive episodes was statistically significant when compared to those in euthymia, the variability was large, and there was considerable overlap between the values of BDNF levels found in mania and depression with those in euthymia." (PMID 26621529, 2015). "In addition to supporting the effects of EA described in other scenarios, such as neuropathic pain and depression, our findings provide a correlate between the clinical effect and a biological marker, the serum BDNF." (PMID 25947167, 2015). "More research on BDNF models in the context of both schizophrenia and depression is needed." (PMID 25762938, 2015). "As well, since BDNF levels are altered in both depression and suicide, it is unclear whether the differences are related specifically to suicide." (PMID 25908105, 2015). "Although several studies have examined the relationships between depression and BDNF or NTRK2, few have examined whether these genes contribute to an individual’s stress-coping style." (PMID 26445699, 2015). "Thus, several studies have examined the relationship between depression and BDNF and NTRK2, although few have examined how these genes contribute to an individual’s vulnerability to stress." (PMID 26445699, 2015). "Thus, by modulating synaptic plasticity throughout the peripheral and central pain circuits, BDNF can alter pain sensitivity and, more importantly, the level of pain-induced depression." (PMID 25810926, 2015). "The association between BDNF Val66Met genotype and different types of depression was not analyzed in this study because no studies analyzed the BDNF Val66Met genotypes and irritability." (PMID 26733829, 2015).
depression (continued). "In a similar approach, the objective of the present study was to evaluate, in a sample of older women, the association of anxiety disorders and/or depression with a specific DNA methylation according to SNVs in four candidate genes: SLC6A4, BDNF, OXTR, and APOE." (PMID 26175754, 2015). "However, our findings support and extend previous results that have principally used blood samples, indicating elevated BDNF promoter methylation in depression." (PMID 26285129, 2015). "Finally, we investigated the release of neurotrophic factors, including IGF-1 and BDNF (brain derived neurotrophic factor), in microglial cells in cultures in an animal model of depression." (PMID 25814933, 2015). "BDNF was downregulated in the hippocampus of a CRS-induced rat depression model." (PMID 26191079, 2015). "BDNF levels are altered in depression and other psychiatric disorders." (PMID 26718989, 2015). "In this study we will investigate the role of the brain-derived neurotrophic factor (BDNF), methylation profile of the BDNF gene (e.g. CpG I and IV) and oxytocin and RNA marker profiles during psychotherapy for depression." (PMID 26122891, 2015). "This evidence indicates that stimulation of BDNF/CREB could provide a new approach to the treatment of depression." (PMID 25618406, 2015). "SSRIs can also alter levels of inflammatory markers and BDNF in patients with depression, so it is difficult to conclude whether our findings would generalize to treatment-naive patients." (PMID 26241349, 2015). "We found a negative association between serum and plasma BDNF levels and severity of manic and depressive symptoms in mania and depression, meaning that the higher the severity of manic or depressive symptoms, the lower the BDNF levels." (PMID 26621529, 2015). "Indeed, a role for BDNF in the pathophysiology and treatment of depression and schizophrenia is strongly supported." (PMID 25762938, 2015). "In Parkinson’s disease patients with depression, levels of BDNF and orexin are down-regulated." (PMID 25884812, 2015). "The data derived from the community dwelling women suggested that moderate exercise, such as a 12-week MAE, could improve depression symptoms, presumably through an increase in BDNF levels." (PMID 26075212, 2015). "This idea rests on the neurotrophin hypothesis, which posits that depressive disorders are secondary to a stress-induced lowered expression of BDNF." (PMID 26529101, 2015). "There is evidence that treatment for depression raises BDNF levels." (PMID 24670553, 2014). "Whether the serum BDNF value of individuals with depression comorbid with diabetes varies with the severity of depressive symptoms, possibly as a biomarker of chronic hyperglycemia-induced neural cell death, would be worth investigating." (PMID 24764190, 2014). "Although single or multiple sleep deprivation therapies have been reported to increase serum BDNF concentration during treatment for depression, the decreased quantity and quality of sleep during the present mission did not affect the significant decrease in plasma BDNF in the current study." (PMID 24586790, 2014). "Therefore, further study on the long-term effects of lifestyle intervention on BDNF and depression are warranted." (PMID 24524285, 2014). "According to the ‘neurotrophic hypothesis’ of depression, stress reduces BDNF activity, which results in decreased function in limbic brain regions (for example, hippocampus) involved in emotion processing and cognition." (PMID 24433458, 2014). "Therefore, the effects of BDNF on depression-like behavior depend upon the functional role of the circuitry that is targeted." (PMID 24817844, 2014). "In addition, sleep deprivation, which is sometimes used in depression therapy, has been reported to increase serum BDNF concentration." (PMID 24586790, 2014). "Reduction in BDNF levels has also been indicated in various mental disorders including depression." (PMID 24550703, 2014).